HSH2D (hematopoietic SH2 domain containing)
Description:
May be a modulator of the apoptotic response through its ability to affect mitochondrial stability (By similarity). Adapter protein involved in tyrosine kinase and CD28 signaling. Seems to affect CD28-mediated activation of the RE/AP element of the interleukin-2 promoter.
Synonyms: ALX; HSH2; FLJ14886
Tractability: Antibody: the Human Protein Atlas places it where antibodies can reach. PROTAC: ubiquitination databases record sites on it; its protein half-life has been measured.
Gene: Protein-coding gene on chromosome 19 (16,134,028 to 16,158,575, forward strand). Ensembl gene ENSG00000196684.
Subcellular location: Cytoplasm; Nucleus
Subcellular location (Human Protein Atlas): Plasma membrane; Cytosol; Focal adhesion sites
Gene Ontology:
Molecular function: protein binding; protein-macromolecule adaptor activity
Biological process: T cell activation; signal transduction
Cellular component: cytoplasm; cytosol; mitochondrion; nucleus
Genetic constraint (gnomAD): Loss-of-function variants: 11 observed, 16.41 expected, observed/expected ratio (o/e) 0.67, 90% interval 0.42 to 1.11. The upper end of that interval is the gene's LOEUF score, 1.11, which puts it in group 4 of 6, group 1 being the genes least tolerant of losing a copy. Missense variants: 395 observed, 408.27 expected, observed/expected ratio (o/e) 0.97, 90% interval 0.89 to 1.05. Synonymous variants: 163 observed, 170.67 expected, observed/expected ratio (o/e) 0.96, 90% interval 0.84 to 1.09.
Homologues: Orthologues: chimpanzee HSH2D (99% identical), macaque HSH2D (92% identical), pig HSH2D (66% identical), dog HSH2D (65% identical), rabbit HSH2D (60% identical), mouse Hsh2d (52% identical), rat Hsh2d (50% identical), zebrafish hsh2d (29% identical), tropical clawed frog hsh2d (28% identical), Caenorhabditis elegans F13B12.6 (13% identical), zebrafish zgc:92242 (11% identical). Paralogues in human: SH2D2A (20% identical), SH2D7 (20% identical), SH2D4B (16% identical), SH2D4A (14% identical).
Diseases named in the same sentence as HSH2D in open-access papers:
HSH2D is named in the same sentence as 7 diseases in open-access papers, as found by Europe PMC text mining. Sharing a sentence is not in itself a finding about the gene and the disease. The quoted sentences say what the papers report.
bladder cancer (1 paper, 2025). "In the present study, we constructed a novel and highly reliable four-gene marker (OAS1, AOC2, HOXB5, and HSH2D) for predicting the prognosis of bladder cancer based on TPECs-related genes." (PMID 41584451, 2025).
colorectal cancer (1 paper, 2024). A primary or metastatic malignant neoplasm that affects the colon or rectum. "Additionally, DOX-persisting proliferative cells marked by a U‐ISGF3-gene signature upregulate the HSH2D gene – a poor prognostic marker in colorectal cancer (Human Protein Atlas proteinatlas.org)." (PMID 39405604, 2024). "Public data (Human Protein Atlas proteinatlas.org) showed that high expression of HSH2D correlates with a significantly lower 5-year survival rate in colorectal cancer patients (65 % for patients with low expression of HSH2D vs. 47 % for high expression; P= 9.5e-6)." (PMID 39405604, 2024). "Interestingly, HSH2D expression did not correlate with other genes associated with colorectal cancer metastasis and tumorigenesis, namely CDC20 and BIRC5." (PMID 39405604, 2024).
prostate intraepithelial neoplasia (1 paper, 2022). A neoplastic proliferation of the epithelial cells that line the acini and the ducts of the prostate gland. "As well as driving the formation of prostate intraepithelial neoplasia, overexpression of TF MYC could further suppress target gene HSH2D." (PMID 35164166, 2022).
tumor (3 papers, 2019 to 2022). "Since target gene HSH2D plays an important role in T cell activation, its low expression could reduce the activity of anti-tumor T cells." (PMID 35164166, 2022). "The results indicated that AIFM3, HSH2D, and PTPN6 were significantly up-regulated, while DCHS1, PTGIS, FLRT2, PCSK5, and CLSTN2 were significantly down-regulated in tumor samples compared with normal samples." (PMID 34512722, 2021).
HSH2D also shares sentences with these, for which no sentence is quoted: Alzheimer disease (1 paper); metastatic tumors (1); periodontitis (1).